BRAF (B-Raf proto-oncogene, serine/threonine kinase)
Diseases named in the same sentence as BRAF in open-access papers (continued):
Sharing a sentence is not in itself a finding about the gene and the disease.
melanoma (continued). "Specific methylation signatures were also found for melanoma tumours harbouring BRAF mutations." (PMID 30651148, 2019). "In addition, they showed that since melanoma-carrying BRAF mutations are reliant on MEK-ERK signalling to a far greater extent than RAS mutants, the former tumours are highly sensitive to pharmacological MEK inhibition." (PMID 31126017, 2019). "However, there still remains a role for adjuvant IFN-α in the setting of BRAF wild-type melanomas and in patients at increased risk of cancer immune escape or autoimmune events with CTLA-4 and PD-1 blocking antibodies." (PMID 30725205, 2019). "The BRAF gene mutation has been identified in melanoma, lung, colon, and thyroid cancers." (PMID 30886831, 2019). "Whether this will translate into a rational to use radiotherapy in the curative setting in BRAF-mutated melanoma patients deserves consideration." (PMID 31374895, 2019). "Hence, we tested the leukocyte fraction and tumor purity in BRAF-mutated and BRAF-wildtype melanoma." (PMID 31747929, 2019). "Similarly, trametinib prolonged the survival of melanoma patients in the Phase III clinical trials ‘COMBI-AD’, and was FDA approved in 2018 for use in combination with dabrafenib for patients with melanomas with BRAF V600E or V600K mutations." (PMID 30975211, 2019). "BRAF mutations are found in many cancers and are particularly common in melanoma." (PMID 31353365, 2019). "They found that BRAF mutations cause the progression of nevi to overt melanoma." (PMID 31531096, 2019). "Downstream consequences of such confounding factors were exemplified in a recent publication, in which the authors inferred a coessentiality network using the Achilles dataset and reported that SOX9 is part of a gene cluster highly specific to BRAF-mutated melanoma cell lines." (PMID 30683138, 2019). "It will be of import to evaluate whether the economic advantage associated with the combination regimen is maintained across key melanoma subgroups categorized by BRAF mutation status and PD-L1 expression levels." (PMID 31312536, 2019). "Targeting of the prevalent BRAF V600E mutation (present in around 50% of patients) with vemurafenib or similar compounds produce clinical responses in most melanoma patients but all patients develop resistance and relapse, highlighting the need of new therapeutic targets." (PMID 30622697, 2019). "Subsequently, agents targeting human epidermal growth factor receptor 2 (HER-2)-overexpressing breast or gastric cancer, BRAF V600E-mutation melanoma, and EGFR-, ALK-, and ROS1-mutation lung cancer enables patients with those molecular alterations to have a significantly prolonged life expectancy." (PMID 31032221, 2019). "In V600 BRAF-mutant melanoma cells, loss of E-cadherin occurs frequently and it could be responsible for higher metastatic activity." (PMID 31514305, 2019). "E-cadherin loss occurs frequently in V600E BRAF-mutant melanomas." (PMID 31514305, 2019). "Indeed, immunohistochemical analysis for VE1 mutation was recommended as a predictable methodology for detection of BRAF V600E mutation in alternative tumors like melanoma, papillary carcinoma of the thyroid, and colorectal carcinoma." (PMID 31781475, 2019). "The BRAF/MEK inhibitor combination is already approved for melanoma with BRAF mutation." (PMID 31500314, 2019). "al. detected BRAF V600E mutations in 70.1% of melanoma patients." (PMID 31531096, 2019). "Furthermore, we also found different MITF levels in melanoma cell lines harboring BRAF mutations, as compared to wtBRAF." (PMID 30634982, 2019). "Three of the most important targeted therapies used in the clinic are vemurafenib, trametinib, dabrafenib and some of their combinations, which are FDA approved regimens for melanoma treatment acting by blocking BRAF with activatory mutations, such as V600E or V600K." (PMID 32309611, 2019).
melanoma (continued). "In this study, we analyzed phosphorylation, localization and conformational variations of the eIF2α subunit in metastatic melanoma cell lines with different BRAF mutational status, evaluating potential correlation with other pathways involved in the invasive phase of melanoma." (PMID 30634982, 2019). "MD simulations have been performed for exploring the molecular character of BRAF protein, establishing the differences between the wild-type BRAF and mutant BRAF(V600E) protein to unravel the underlying mechanisms of the inhibitor resistance in malignant melanoma." (PMID 30871264, 2019). "MAPK pathway is estimated to be deregulated in almost 50% of human malignancies, activating mutation of BRAF in 5–10% of cancers, especially hairy cell leukemia, melanoma, colorectal cancer, papillary thyroid cancer, non-small cell lung cancer (NSCLC), and ovarian cancer." (PMID 31450703, 2019). "Overall, our custom sequencing panel targeting commonly mutated genes in melanoma was effective in providing mutational information in most patients, allowing for identification of targetable mutations for ctDNA analyses in patients WT for BRAF and NRAS." (PMID 30312528, 2019). "The rationale for these groupings is that genes with parallel or related functions relevant to melanoma may harbor mutually exclusive mutations, as is the case for BRAF and NRAS, such that they would escape notice when examined individually." (PMID 30956763, 2019). "Of the BRAF mutations observed in melanomas, the V600E mutation is the most common (~90%)." (PMID 31581557, 2019). "Interestingly, modulation of autophagy has been postulated to be a potential mechanism of adaptive resistance to MAPKi in sensitive and resistant BRAF-mutated melanoma cells." (PMID 30254376, 2019). "Major genetic drivers of melanoma oncogenesis are the gain-of-function mutations of B-Raf (BRAF), neurofibromin 1 (NF1), and NRAS, which contribute to the activation of the ERK/MAPK pathway, resulting in the uncontrolled growth, proliferation, and enhanced survival of tumor cells." (PMID 31426515, 2019). "The safety and efficacy of combined vemurafenib and MEK inhibitor cobimetinib in patients with advanced BRAF-mutated melanoma were also assessed; when administered at their respective maximum tolerated doses, vemurafenib and cobimetinib co-therapy was safe and well tolerated (NCT01271803)." (PMID 31775797, 2019). "Using melanoma cells with intrinsic and acquired resistance to vemurafenib, we demonstrate here the combination of radiotherapy and a BRAF inhibitor to cause a radiation dose-dependent decrease in cell survival, and consequently an increase in cell death in vitro." (PMID 31374895, 2019). "Mutated proto-oncogene BRAF is a bona fide therapeutic target for melanomas." (PMID 30745871, 2019). "Sixty five consecutive formalin-fixed paraffin-embedded (FFPE) melanoma samples were prospectively tested for BRAF mutations with the VE1 (anti-BRAF V600E) antibody and for both BRAF and NRAS mutations with the Idylla NRAS-BRAF-EGFR S492R Mutation Assay cartridges." (PMID 31415669, 2019). "In our single-center analysis, we retrospectively analyzed the pattern of progression of 214 MM patients treated with anti-BRAF plus anti-MEK targeted drugs for BRAF-mutated melanoma or with PD1 inhibitors, and we found a 10% incidence of oligoprogression (27 patients)." (PMID 31615127, 2019). "Our study revealed a subjacent layer of heterogeneity in V600E BRAF-mutated melanomas." (PMID 31835364, 2019). "Indeed, the secretion of tumor-necrosis-factor α (TNF-α) and IL-12 by dendritic cells is inhibited when they are co-cultured with melanoma, cells either BRAF mutated or wild-type." (PMID 31762942, 2019). "Categorization of 3 classes of BRAF mutations according to their mechanisms of signal transduction to activate MAPK pathway showed sun damage could contribute to tumorigenesis of melanomas carrying the BRAF p.V600K mutation or class-3 BRAF mutations." (PMID 31277584, 2019).
melanoma (continued). "The findings reported here suggest that SRF/MRTF inhibitors, in combination with BRAF inhibitors, could have utility in the treatment of BRAF mutant melanoma with an additional RAC1P29S mutation." (PMID 31257073, 2019). "BRAF-inhibition has become the standard of care in BRAFV600E-mutated melanoma." (PMID 31391125, 2019). "A high percentage (66%) of malignant melanomas carry the V600E BRAF gene mutation." (PMID 31091806, 2019). "Similarly to NRAS, BRAF mutations suggest the existence of genotoxic agents in mucosal melanoma, which remain to be identified." (PMID 31398831, 2019). "The frequency of BRAF mutation in our cohort was similar to previous melanoma cohorts." (PMID 30931305, 2019). "BRAF-V600E is the most common activating mutation found in melanoma." (PMID 31886081, 2019). "The analyses presented here for the BRAF-mutant melanoma cells might suggest that identifying drug susceptibilities in each of the cancer cell phenotypes might lead to a more effective therapy." (PMID 31166947, 2019). "Besides PIK‐75, in combination therapy we utilized vemurafenib, currently used in patients with BRAF‐mutated advanced melanoma." (PMID 31115969, 2019). "Inhibitors for the protein have been developed as therapeutic targets for BRAF‐mutated melanomas." (PMID 30499222, 2019). "In melanomas, the most commonly mutated oncogene is BRAF present in more than 50% of tumors." (PMID 31039200, 2019). "In a patient with melanoma, we identified a kinase-inactivating BRAF mutation." (PMID 32913998, 2018). "Vemurafenib is a BRAF inhibitor specifically targeting melanomas carrying the BRAF V600E mutation." (PMID 30463359, 2018). "It is of paramount importance that a patient’s BRAF mutational status is promptly and accurately determined at the time of initial diagnosis, because it is currently the only reliable predictive biomarker that can influence the treatment of advanced melanoma." (PMID 29148538, 2018). "This study aimed to explore whether melanoma patients with BRAF or NRAS mutant tumours have an increased risk of developing disease recurrence following a negative SLNB compared to patients with wild-type tumours." (PMID 29755118, 2018). "BRAF inhibitors are the first line of therapy for melanoma cases harboring oncogenic BRAF mutation." (PMID 29394289, 2018). "Among Chinese patients with melanoma, the rate of BRAF mutation is approximately 25%." (PMID 29724167, 2018). "Similarly, reduced viability was observed in a panel of melanoma BRAF-mutated cells (MM96L, A2058, HTT144, JA, SKMEL28 and A02) at 50 μg/mL, with a more profound effect observed for HiGom." (PMID 30068931, 2018). "For example, of the approximately 50% of melanoma patients whose tumors carry mutations in BRAF, nearly 90% have a substitution at amino acid position 600, and 90% of these substitutions are V600E, which occurs only from a nucleotide position 1799 T → A substitution." (PMID 29854275, 2018). "Further, we performed chemosensitivity arrays 72 h after treatment of SKMEL28 and 451LU melanoma cells (both carrying a BRAF mutation) with the BRAF-antagonist dabrafenib in combination with the MEK-inhibitor trametinib in combination with agonists and antagonists." (PMID 29716947, 2018).
melanoma (continued). "BRAF was found mutated in 20/32 (62.5%) cell lines, with identical distribution of mutation frequencies between those derived from primary (5/8; 62.5%) and those derived from metastatic (15/24; 62.5%) melanomas." (PMID 29492214, 2018). "Almost 50% of malignant melanomas have somatic mutation of BRAF gene." (PMID 30255823, 2018). "Importantly, we demonstrate that USP28 expression is deleted in ∼10% of all melanoma patients, of which half of these patient’s harbor mutations in BRAF (V600E), NF1, or NRAS, supporting a role for USP28 loss in melanoma progression." (PMID 29880484, 2018). "We then evaluated eNAMPT in 163 patients with BRAF-mutated melanoma." (PMID 29721178, 2018). "However, promising clinical efficacy of Vemurafenib has been reported in a recent phase 2 “basket” trial of vemurafenib in patients with non-melanoma cancers harboring BRAF V600E mutations." (PMID 29416679, 2018). "Samples from 13 patients with a BRAF or KRAS variant present in solid tumor tissue from melanoma (N = 8), colorectal adenocarcinoma (N = 3), or pancreatic ductal adenocarcinoma (N = 2) and a corresponding quantifiable variant present in ccfDNA by ddPCR were analyzed." (PMID 30044795, 2018). "Thanks to the recent advances in deep sequencing, melanomas are now classified at the molecular level depending on the mutational status of their major oncogenic drivers (BRAF, NRAS, and NF1), and are considered as “triple-negative” when no mutations are present in these genes." (PMID 29534457, 2018). "In this open-label phase 2 trial we sequenced the BRAF inhibitor vemurafenib with HD IL-2 in the treatment of patients with stage IV, metastatic BRAF-mutated malignant melanoma and assessed the toxicity and efficacy specifically with regard to the complete response rate from this combination." (PMID 30053905, 2018). "Starting from these observations, we measured eNAMPT levels in melanoma cell lines and in a large cohort of patients with BRAF-mutated metastatic melanomas, before and after therapy, suggesting that eNAMPT is a novel disease marker in BRAF-mutated melanoma patients." (PMID 29721178, 2018). "Of note, BRAF p.V600E mutations more commonly arise than p.V600M mutations in melanomas." (PMID 30412573, 2018). "Notably, the finding that the common V600 mutation in BRAF in melanoma is irrelevant to pyroptosis reveals the potential application of pyroptosis for melanoma treatment." (PMID 30287942, 2018). "In some melanomas, and particularly those with a low contribution from signature 7, we suggest that BRAF p.V600E mutations may also arise independently from UV radiation-associated mutagenesis." (PMID 30412573, 2018). "A data series of 274 patients with BRAF-mutated melanoma who sequentially received BRAF inhibitors and immunotherapy (high-dose IL-2, ipilimumab, or PD-1 inhibitors) illustrated that ipilimumab therapy after BRAF inhibitors was associated with no tumor response and poor survival." (PMID 29848375, 2018). "In melanoma, coexistence of BRAF V600E and TERT promoter mutations was associated with increased tumor thickness, high mitotic rate, lymph node metastasis, presence of ulceration, absence of regression, high risk of tumor recurrence, and melanoma-specific mortality." (PMID 29422527, 2018). "Most patients with stage I, II, or III melanoma indicated to be unfamiliar with any mutations present in their tumour, compared to 46% of patients with stage IV melanoma and 53% of carers who indicated that a BRAF mutation had been found in the tumour." (PMID 30497502, 2018). "We further classified the 89 samples into the four molecular subtypes, BRAF mutated (47% in melanoma TCGA), RAS mutated (NRAS/KRAS/HRAS mutations, 29%), NF1 mutated (9%), and Triple-WT (subgroup lacking above mutations, 15%), proposed by the recent TCGA melanoma cohort." (PMID 30373548, 2018).
melanoma (continued). "In 40–60% of all melanoma patients, mutational activation of BRAF V600E can be found, resulting in constitutive activation of the serine-threonine protein kinase BRAF and the Ras-RAF-MEK-ERK signaling pathway, also known as mitogen activated protein (MAP) kinase pathway." (PMID 29541007, 2018). "The combined therapy using cobimetinib and vemurafenib improved the median OS, PFS and the ORR in unresectable stage IIIC or stage IV melanoma patients harboring BRAF V600E mutations when compared with vemurafenib monotherapy, demonstrating the clinical benefit of this treatment." (PMID 29455659, 2018). "The genetic basis of melanoma development is fairly well understood, with activating mutations in the oncogene BRAF occurring in a majority of melanoma patient tumors, which also harbor hundreds of secondary mutations of unknown impact." (PMID 30349559, 2018). "Vemurafenib was the first FDA approved BRAF-inhibitory therapy for BRAF mutated melanoma." (PMID 29946532, 2018). "In another study of 93 patients with BRAF-mutated melanoma who received BRAF inhibitors (vemurafenib or dabrafenib) before or after ipilimumab, longer OS was found in the cohort of patients receiving ipilimumab prior to BRAF inhibitor therapy (14.5 vs. 9.9 months, P = 0.04)." (PMID 29848375, 2018). "These mutations account for approximately 95% of BRAF mutations found in melanoma." (PMID 29879227, 2018). "Oncogenic mutations in the oncoprotein BRAF, which encodes the growth signal transduction serine/threonine protein kinase B-Raf, are found in approximately 50% of melanomas and result in constitutive activation of the RAS/mitogen-activated protein kinase (MAPK) pathway." (PMID 30154763, 2018). "Importantly, the MIFT-PGC-1α-ID2/3 axis in under the control of the BRAF (V600E) oncogene, the most frequent BRAF mutation in melanoma." (PMID 29629336, 2018). "The present study was aimed at identifying signaling pathways that may dictate the migration strategy used by BRAF V600E-mutated human melanoma cells." (PMID 29379163, 2018). "In most cases, BRAF-resistant melanomas bear additional mutations, reactivating the MAPK pathway." (PMID 30274263, 2018). "Our findings raise the hypothesis that combining bevacizumab with adjuvant immune checkpoint inhibitors may benefit high-risk BRAF mutant melanoma patients, who in our study had a poorer prognosis than patients with tumours lacking the mutation." (PMID 30010756, 2018). "Over 50% of melanomas harbor various BRAF mutations with the most common being the V600E." (PMID 29795041, 2018). "BRAF-mutated melanomas were present in 38 patients (39.1%); 54 (55.7%) had BRAF wild-type tumors." (PMID 30012216, 2018). "Taken together, our previous results imply and justify the application of PT methods to study potential mechanism of melanoma development in more detail and particularly to disentangle common and different properties of tumor progression dynamics associated with BRAF- and NRAS-mutations." (PMID 29614062, 2018). "However, at present, the beneficial effects of BRAF inhibitors in melanoma patients bearing BRAF V600 mutations are well established." (PMID 29371600, 2018). "In this phase I multicenter, international, open-label, randomized expansion of the KEYNOTE-001 cohort, 173 patients with advanced or unresectable melanoma who had previously failed treatment with ipilimumab and a BRAF inhibitor (if BRAFV600-mutated) were treated with pembrolizumab." (PMID 29357948, 2018). "Gene mutations, mostly BRAF mutations, are present in over half of all human melanomas." (PMID 29976230, 2018). "Analyzing BRAF V600E mutation in circulating melanoma cells by IHC is also possible." (PMID 29879227, 2018). "However, since BRAF mutated melanomas are the only subset in which a target therapy has been approved, we focused subsequent studies in this subset." (PMID 30558661, 2018).